RNU6-170P (RNA, U6 small nuclear 170, pseudogene)
Gene: Small nuclear RNA gene on chromosome 18 (12,304,091 to 12,304,194, reverse strand). Ensembl gene ENSG00000199702.
Homologues: Orthologues: chimpanzee U6 (98% identical), macaque U6 (86% identical). Paralogues in human: RNU6-1316P (90% identical), RNU6-1145P (89% identical), RNU6-38P (89% identical), RNU6-434P (89% identical), RNU6-20P (88% identical), RNU6-29P (88% identical), RNU6-310P (88% identical), RNU6-35P (88% identical), RNU6-1031P (88% identical), RNU6-1083P (88% identical), RNU6-1175P (88% identical), RNU6-1310P (88% identical), and 1288 more.